PRL (prolactin)
Diseases named in the same sentence as PRL in open-access papers (continued):
Sharing a sentence is not in itself a finding about the gene and the disease.
endothelial dysfunction (18 papers, 2013 to 2026). In vascular diseases, endothelial dysfunction is a systemic pathological state of the endothelium (the inner lining of blood vessels) and can be broadly defined as an imbalance between vasodilating and vasoconstricting substances produced by (or acting on) the endothelium. "Levels of PRL, and by extension, lactogenic signaling via the PRLR, are not consistently associated with the risk of cardiovascular events, even though excess prolactin elevates the risk of endothelial dysfunction and metabolic disorders." (PMID 39796124, 2024). "Independently from miR-146a, 16-kDa PRL causes endothelial dysfunction by inducing caspase-dependent apoptosis, as well as decreasing the synthesis of inducible nitric oxide synthase (iNOS) and, subsequently, nitric oxide (NO) production." (PMID 38254703, 2024). "PRL levels are directly associated with endothelial dysfunction and increased risk of cardiovascular events and mortality in CKD." (PMID 35173591, 2022). "Additionally, the serum level of prolactin and prolactin receptor, supposedly associated with endothelial dysfunction, pathological remodeling, and compromised cardiovascular health, was significantly reduced by ARNI and slightly by captopril." (PMID 38672089, 2024). "PRL was also implicated in endothelial dysfunction in pre and postmenopausal women." (PMID 36704037, 2022). "Through unknown mechanisms, increased levels of oxidative stress cause a cleavage of prolactin into a 16-kDa fragment, which causes endothelial dysfunction and induces cardiomyocyte apoptosis." (PMID 33555408, 2021). "In PPCM, oxidative stress is thought to trigger cathepsin D to cleave 23‐kDa prolactin into a 16‐kDa fragment, which leads to endothelial dysfunction through the up‐regulation of miRNA‐146a." (PMID 40654268, 2025). "Elevated prolactin levels can lead to endothelial dysfunction, characterized by impaired NO production, which is essential for vascular relaxation and increased blood flow to the penis." (PMID 40966237, 2025). "On the one hand, 16-kDa PRL enhances endothelial dysfunction, and on the other hand, disturbs the metabolism of cardiomyocytes." (PMID 38254703, 2024). "Endothelial dysfunction is a major player in developing PH, and tremendous evidence provided earlier has demonstrated that PRL/vasoinhibins regulate EC function." (PMID 35923071, 2023). "Although both FSH and PRL individually promote stiffness and endothelial dysfunction, their combined ratio may facilitate a net reduction in DBP." (PMID 41555389, 2026). "In an observational study including 457 normoprolactinemic non-dialyzed CKD patients and 173 hemodialysis patients, PRL levels were directly associated with endothelial dysfunction/stiffness and with increased risk of cardiovascular events and mortality." (PMID 36704037, 2022). "Meanwhile, several in vitro studies indicated a direct effect of PRL on ECs,57 smooth muscle cells, fibroblasts, and other cells, which eventually may lead to endothelial dysfunction, pathologic vascular tone, arterial stiffening, increased BP, and further end‐organ disease." (PMID 35923071, 2023). "In vitro studies have shown that PRL can modulate inflammatory responses, stimulate vascular smooth muscle cell proliferation, and play a role in the adhesion of circulating mononuclear cells to endothelium, pointing to a role of PRL in endothelial dysfunction." (PMID 36704037, 2022). "Moreover, increased plasma levels of Cathepsin D, ADMA and miRNA-146a support the hypothesis that a circuit involving Prolactin cleavage and subsequent endothelial dysfunction acts as a major pathophysiological concept for this disease." (PMID 23812247, 2013).
Hepatic steatosis (18 papers, 2019 to 2025). Steatosis is a term used to denote lipid accumulation within hepatocytes. "After that, the mechanisms involved in the desynchronization of hepatic PRL signaling in SJL-induced fatty liver were explored." (PMID 40462123, 2025). "Our work emphasized that PRL played an important role in mediating SJL related fatty liver and that the timing of drug therapy should be taken into consideration in optimizing MASLD treatment." (PMID 40462123, 2025). "It has been found that PRL prevents hepatic steatosis in male mice on a high-fat diet and reduces TG accumulation in the liver of female mice." (PMID 39682330, 2024). "PRL levels were significantly lower in patients with severe hepatic steatosis as compared to those with mild-to-moderate hepatic steatosis in both sexes." (PMID 36237192, 2022). "Prolactin acts on these receptors to prevent hepatic steatosis by decreasing triglyceride accumulation." (PMID 36246929, 2022). "Patients with NAFLD show lower PRL levels than control subjects and those with severe hepatic steatosis have even lower PRL values than patients with a mild to moderate disease." (PMID 36213259, 2022). "Lower PRL levels were found in patients with severe hepatic steatosis compared with those displaying mild and moderate hepatic steatosis." (PMID 33716958, 2021). "We further determined the incremental predictive value of adding PRL in our model for identifying subjects with hepatic steatosis." (PMID 31775658, 2019). "Importantly, the inhibition of PRL by bromocriptine or by knocking out Prl in vivo under JL showed a similar degree of liver steatosis compared with their counterparts." (PMID 40462123, 2025). "Restoration of PRL rhythm could effectively alleviate SJL-induced fatty liver, providing new insight into treating MASLD." (PMID 40462123, 2025). "Importantly, when dynamically monitored, we observed lower serum PRL levels after 9 weeks, and liver steatosis after 15 weeks of SJL." (PMID 40462123, 2025). "Thus, these photothermal‐responsive core–shell microneedles with prolactin pulse release hold significant promise for the treatment of fatty liver disease." (PMID 40586298, 2025). "In the liver, PRL ameliorates hepatic steatosis via the CD36 pathway." (PMID 39682330, 2024). "In humans, PRL has also been shown to ameliorate hepatic steatosis via the CD36 pathway." (PMID 39682330, 2024). "By acting through hepatic PRL receptors, prolactin was demonstrated to reduce liver steatosis." (PMID 39425884, 2024). "Additionally, prolactin levels were lower in men and women with severe hepatic steatosis compared to patients with only mild hepatic steatosis." (PMID 36860364, 2023). "On the contrary, cross-sectional retrospective studies in patients without pituitary disorders showed that low prolactin concentrations are associated with an increased risk for hepatic steatosis." (PMID 36860364, 2023). "Likewise, the results showed that females with liver steatosis and significant fibrosis had significantly lower serum PRL levels in the NP group but higher serum PRL levels in the HP group." (PMID 35222274, 2022). "In addition to its role in hepatic steatosis, prolactin has been shown to impact insulin sensitivity." (PMID 36246929, 2022). "Thus, we assessed liver steatosis and significant fibrosis using FibroScan and explored their correlations with serum PRL in both genders." (PMID 35222274, 2022). "Regarding fatty liver in other populations, further investigations focusing on the hepatic effects of prolactin may also shed new light on mechanisms designed to reduce liver fat in men and women with metabolic diseases." (PMID 36162520, 2022). "Furthermore, prolactin levels were found to be lower in patients with severe hepatic steatosis when compared to patients with mild to moderate disease." (PMID 36246929, 2022).
Hepatic steatosis (continued). "Moreover, the results revealed a novel association between the central nervous system and liver, whereby PRL/PRLR improved hepatic steatosis via the CD36 pathway." (PMID 33716958, 2021). "Importantly, restoration of PRL rhythm could alleviate SJL induced fatty liver more effectively compared with conventional PRL administration." (PMID 40462123, 2025). "Thus, the released prolactin in mice consuming a high‐fat diet (HFD) can mitigate hepatic steatosis through its interaction with the hepatic prolactin receptor (PRLR) and by modulating the expression of CD36, a pivotal fatty acid translocase (FAT) of free fatty acid (FFA) uptake." (PMID 40586298, 2025). "However, a previous study has shown that PRL intervention could also reduce hepatic steatosis in male mice under HFD." (PMID 40462123, 2025). "In addition, PRL promotes hepatic insulin sensitivity and prevents hepatic steatosis." (PMID 40687581, 2025). "In addition, circulating PRL is involved in regulating lipid storage in the liver, and serum PRL was reported to be reduced in patients with non‐alcoholic fatty liver disease and hepatic steatosis as compared to healthy controls." (PMID 39663784, 2024). "In population-based studies, a high-normal serum PRL within the normal physiological range is associated with a lower risk of T2DM and improved visceral fat dysfunction and IR and negatively associated with NAFLD and severity of hepatic steatosis in both men and women." (PMID 35222274, 2022). "Disrupted PRL rhythm caused by impaired transcriptional regulation of RORα in the pituitary, accompanied by disturbed oscillation of PRL signaling pathway and the resulting heightened lipogenesis in the liver, contributed to SJL-induced fatty liver." (PMID 40462123, 2025). "Based on these data, decreased serum PRL levels at ZT12 under SJL might inhibit hepatic CCND1 levels through MAPKs, leading to the activation of lipogenic enzymes (i.e., FASN and ACC) and hepatic steatosis." (PMID 40462123, 2025). "Female but not male patients with MAFLD, liver steatosis, and fibrosis had significantly lower PRL levels in the NP group but higher PRL levels in the HP group than their counterparts." (PMID 35222274, 2022). "Furthermore, serum PRL levels were altered significantly in females with MAFLD, liver steatosis, and significant fibrosis compared with their counterparts and were unchanged among males." (PMID 35222274, 2022). "The proportions of MAFLD, liver steatosis, and fibrosis were significantly decreased in the NP group but increased in the HP group across the PRL quartiles in females but not in males." (PMID 35222274, 2022). "Also, the proportions of liver steatosis and significant fibrosis presented a remarkably decreasing trend in the NP group but an increasing trend in the HP group with the increment of serum PRL levels among females but not males." (PMID 35222274, 2022). "It was also observed that PRL/PRLR could reduce stearoyl–coenzyme A desaturase 1 (SCD1) expression in various hepatic cell lines and animal models, which is the rate-limiting enzyme in monounsaturated fatty acid biosynthesis, thereby leading to the amelioration of hepatic steatosis." (PMID 36526972, 2022). "Likewise, females with hepatic steatosis or significant fibrosis presented remarkably lower serum PRL levels in the NP group (P < 0.001, P = 0.023, respectively) but higher serum PRL levels in the HP group (all P < 0.001) as opposed to their counterparts, which was not shown among males." (PMID 35222274, 2022).
Oligomenorrhea (18 papers, 2008 to 2026). Infrequent menses (less than 6 per year or more than 35 days between cycles). "Such an evaluation should be undertaken only after other causes of oligomenorrhea have been excluded by proper evaluation of factors such as TSH, prolactin, and 17-OHP, and possibly FSH and LH, in accordance with the 2023 International Guidelines." (PMID 39419927, 2025). "In contrast, P1 had a history (1.5 years before FGA diagnosis) of oligomenorrhea, multicystic ovaries (135 mL and 129 mL) with increased endometrial thickness (17.3 mm), and serum prolactin > 200 ng/mL." (PMID 37988667, 2023). "Since prolactin is a factor for folliculogenesis and oligomenorrhea, the decrease of its level can be effective in the treatment of PCOS." (PMID 34466481, 2019). "One child was found to have experienced oligomenorrhea - a prolactin-related adverse event – following treatment with risperidone, but analysis was inconclusive as to the relative risk of this event between groups (RR 0.97, CI 0.89 to 1.05, p = 0.44)." (PMID 26611280, 2015). "Hirsutism in 8 of 10 patients having raised serum prolactin levels appears to be more of PCOS associated hyperandrogenism in view of additional features such as elevated free serum testosterone, LH-FSH ratio, oligomenorrhea and/or polycystic ovaries." (PMID 19882006, 2008). "Six patients with secondary amenorrhea or oligomenorrhea had low-normal-to-normal LH, normal FSH, E2, T, free T, PRL, and thyroid function test results, with adequate pubertal development and bone age for their chronological age." (PMID 39981087, 2025).
pituitary cancer (18 papers, 2009 to 2025). A primary or metastatic malignant neoplasm affecting the pituitary gland. "In a literature review, corticotroph carcinomas were shown to be the most common (34.7%) among pituitary carcinomas, followed by prolactin-secreting (23.6%) and null cells (15.3%)." (PMID 34220707, 2021). "In pituitary carcinomas, the most aggressive tumoral nature, corticotroph carcinomas followed by or along with PRL-secreting pituitary carcinomas are the most common features." (PMID 34220707, 2021). "Medical treatment with DA plays a role as first-line therapy of PRL-producing pituitary carcinomas to reduce the tumor volume." (PMID 32760348, 2020). "Among extremely rare pituitary carcinomas, PRL-producing pituitary carcinomas are the most common subtypes following ACTH-producing tumors." (PMID 32760348, 2020). "Pituitary carcinomas are very rare tumors that in most cases produce prolactin and adrenocorticotropic hormone (ACTH)." (PMID 26366311, 2015). "Additionally, lncRNA‐UCA1 can promote pituitary cancer cell growth by enhancing the secretion of prolactin." (PMID 36606322, 2023). "This case suggests that highly sustained serum prolactin levels during the dopamine agonist may indicate prolactin-producing pituitary carcinomas with hidden metastases." (PMID 32760348, 2020). "Similar to our findings, most pituitary carcinomas are either prolactin or ACTH-secreting." (PMID 32622369, 2020). "This metastasis led to the diagnosis of prolactin-producing pituitary carcinoma." (PMID 29928263, 2018). "Currently, the most widely used clinical drugs include dopamine agonists, octreotide and lanreotide, which have been used to treat PRL-, GH-, ACTH- and TSH-secreting pituitary carcinomas." (PMID 25494704, 2014). "Among the secreting pituitary carcinomas, 42% produce ACTH while others produce PRL, growth hormone (GH), luteinizing hormone, follicle-stimulating hormone and thyroid-stimulating hormone." (PMID 24520294, 2014). "According to a recent study, most of the reported pituitary carcinomas are functional (83%), with 35% of the lesions producing ACTH, 33% PRL, 9% growth hormone (GH), 4% luteinizing hormone (LH) and/or follicle-stimulating hormone (FSH), and only 1% TSH." (PMID 25494704, 2014). "Liver masses were eventually confirmed as metastases from prolactin-producing pituitary carcinoma and not from GIST by percutaneous biopsy." (PMID 32760348, 2020). "Pituitary carcinomas commonly produce either PRL or ACTH, but some do not produce pituitary hormones." (PMID 23091742, 2012).
thyroid (18 papers, 2015 to 2025). "Thyroid cancer, goitre (thyroid volume > 18 mL), or other morphological thyroid abnormalities, such as nodules or elevated basal prolactin concentration > 25 ng/mL, are also possible causes and are excluded." (PMID 34513447, 2021). "Thyroid cancer, goiter (thyroid volume > 18 mL), or other morphological thyroid abnormalities, such as nodules or elevated basal prolactin concentration > 25 ng/mL, are also possible causes and were excluded." (PMID 34513447, 2021). "Serum testosterone and DHEAS levels were lower while serum prolactin levels were higher in women with postpartum thyroiditis than in healthy subjects." (PMID 40428279, 2025). "Metformin decreases elevated prolactin levels, which are frequently found in patients with thyroid disorders." (PMID 37297964, 2023). "Between-group differences in the impact on plasma prolactin were accompanied by different effects of metformin on glucose homeostasis markers, gonadotropins and hsCRP, less pronounced in individuals with thyroiditis." (PMID 37297964, 2023). "In pathophysiological conditions such as thyroid disorder, vasoactive intestinal polypeptide stimulates PRL synthesis and thyrotropin-releasing hormone increases secretion; in renal impairment, it decreases PRL clearance and increases serum PRL levels." (PMID 35339194, 2022). "It has been proposed that thyroid function and prolactin can modulate and interact with the male genital tract even within the normal range." (PMID 32728148, 2020). "We report the differential prolactin levels among male and femalepatients with thyroid-related complains in the Hail regions of Saudi Arabia." (PMID 31787812, 2019). "The second aim of our study was to evaluate prolactin homogeneity in different thyroid disorders during pregnancy." (PMID 26091810, 2015). "Though we have restricted our population to eliminate a few confounders such as pregnancy, lactation, thyroid disorders, use of statins, PRL secretagogues/secretion inhibitors, and adjusted for sex, residual confounding might be present due to these factors." (PMID 35509763, 2022). "At the end of the study, both groups differed in prolactin (both total and monomeric), HOMA1-IR, thyroid antibody titers, uric acid, hsCRP, fibrinogen, homocysteine, UACR, and FRS." (PMID 39852352, 2025). "After treatment of thyroid disease, complete resolution of HPRL was reported in 38 (70.4%) patients and improvement in serum prolactin levels in 10 (18.5%) patients." (PMID 39754184, 2025). "The study showed a decrease in prolactin concentrations in men aged between 50 and 75 years with elevated levels of this hormone who do not have concurrent thyroid disease." (PMID 39204081, 2024). "The current study has shown that six-month metformin treatment decreased prolactin levels in hyperprolactinemic women without thyroid pathology and that the strength of this effect depended on the degree of prolactin excess." (PMID 37297964, 2023). "Metformin treatment decreased total and monomeric prolactin levels only in women without thyroid disorder but not in euthyroid women with Hashimoto’s thyroiditis." (PMID 37297964, 2023). "We report herein the serum levels of prolactin, luteinizing hormone (LH), FSH, free T3 (FT3), free T4 (FT4), TSH3 in male and female patients suffered from a thyroid disorder.We found that there is a significant difference in the level of prolactin only between male and female patients." (PMID 31787812, 2019). "Metformin treatment did not significantly affect gonadotropin levels, though both groups differed in the strength of the prolactin-lowering effect, and in men without thyroid pathology, the decrease in plasma prolactin positively correlated with the impact of treatment on LH." (PMID 39204081, 2024). "Moreover, metformin-induced reduction in hsCRP was more pronounced in women without thyroid pathology than in women with thyroiditis and correlated with the impact on both total and monomeric prolactin." (PMID 37297964, 2023).